GFAP (glial fibrillary acidic protein)
Diseases named in the same sentence as GFAP in open-access papers (continued):
Sharing a sentence is not in itself a finding about the gene and the disease.
Alzheimer disease (continued). "Specifically, caspase-3 activation in astrocytes is associated with cytoskeletal remodeling in a kainic acid–induced neurodegeneration model, reactive astrocytes following excitotoxic NMDA-induced neurodegeneration, and GFAP cleavage in an Alzheimer’s disease model." (PMID 35451371, 2022). "Elevated circulating levels of GFAP have been linked to a number of such neurological conditions including traumatic brain injury (TBI), spinal cord injury, multiple sclerosis (MS), Alzheimer’s Disease (AD), Alexander disease, Parkinson’s disease (PD), and neuromyelitis optica spectrum disorder." (PMID 36268187, 2022). "So far, the serum GFAP levels were only shown to be a potential biomarker in intracerebral haemorrhage and ischemic stroke and to correlate with the disease severity in multiple sclerosis, Alzheimer’s disease and NMOSD." (PMID 36009416, 2022). "However, in these studies, the levels of CSF GFAP in Alzheimer’s disease patients, when compared with those of other neurodegenerative diseases, were not significantly different and, therefore, of limited diagnostic value." (PMID 33578866, 2021). "In this study, we investigated the diagnostic performance of plasma GFAP (pGFAP), plasma neurofilament light chain (pNfL) and their combination for frontotemporal dementia (FTD) and Alzheimer’s disease (AD) and their clinical utility in predicting disease progression." (PMID 34893073, 2021). "In contrast, the extent of GFAP expression seems to correspond to the severity of astroglial activation and neurodegeneration in various neuroinflammatory-based disorders, including Alzheimer’s disease, Parkinson’s disease, HIV dementia and multiple sclerosis." (PMID 32964397, 2021). "This cross-sectional cohort study evaluates plasma glial fibrillary acidic protein levels throughout the entire Alzheimer disease continuum, from preclinical Alzheimer disease to Alzheimer disease dementia, compared with cerebrospinal fluid glial fibrillary acidic protein." (PMID 34661615, 2021). "One study investigated GFAP isoforms in a mouse model for Alzheimer’s Disease but did not identify any association with aging or reactive astrocytosis." (PMID 32316287, 2020). "Upregulation of GFAP is the hallmark of mature astrocyte reactivity that occurs in response to an insult or injury in the CNS38,41, which can include chronic neurological conditions such as Alzheimer’s disease, Parkinson’s disease or LSDs42." (PMID 30413728, 2018). "Citrullinated GFAP and vimentin have been noted in Alzheimer’s disease patient." (PMID 30071078, 2018). "Moreover, astrocyte activation and an increase in GFAP are also observed in age-related neurodegenerative disease such as dementia including Alzheimer’s disease." (PMID 28148272, 2017). "While the presence of APP in this report probably reflects neuronal activity, increases in brain APP have also been correlated with increased GFAP in both Alzheimer’s disease and autism and these could also reflect glial activity." (PMID 23803181, 2013). "Along these lines, pathologies such as Alzheimer's disease, Parkinson's disease and amyotrophic lateral sclerosis show increased astrogliosis reactivity with a consequent up-regulation of GFAP levels." (PMID 21985529, 2011). "Additionally, many reports indicate that increase in GFAP may be a marker of neuroinflammation, neurodegeneration and abnormal cognition in Alzheimer’s disease and Parkinson’s disease." (PMID 40779003, 2025). "In this community-based study, we found that cognitively intact older adults with higher levels of p-tau181, p-tau217, NfL, and GFAP face a higher risk of developing both all-cause and Alzheimer's dementia than do those with lower biomarker levels, showing a non-linear dose–response relationship." (PMID 40140622, 2025). "Moreover, GFAP + 1 isoforms expression was observed in specific subtypes of non-reactive astrocytes, characterized by large cell bodies and long processes, with elevated expression in Alzheimer’s disease." (PMID 39554381, 2024).
Alzheimer disease (continued). "Moreover, glial fibrillary acidic protein (GFAP), a marker of glial activation, has been linked to disease severity and poorer progression in Alzheimer’s disease (AD), frontotemporal dementia (FTD), and the alpha-synucleinopathy dementia with Lewy bodies (DLB)." (PMID 39249107, 2024). "In the central nervous system, a group of studies have demonstrated that NDRG2 expression is predominantly present in GFAP-positive astrocytes in brain parenchyma under the physiological or pathological condition and in dystrophic neurons in Alzheimer’s disease." (PMID 37082656, 2023). "Therefore, L-APP detected by proseqff178928 could be used as a blood biomarker for Alzheimer's disease and as a biomarker for therapeutic efficacy since it is derived from astrocytes as well as GFAP and is detected more frequently in SAD than in NCI." (PMID 38066066, 2023). "To more quantitatively investigate whether inflammatory reactive astrocytes are specifically adjacent to inflamed vessels, we probed tissue sections from an Alzheimer’s disease (AD) cohort and asymptomatic age-matched controls for GFAP, GBP2, and VCAM-1 expression." (PMID 36323693, 2022). "Cultured human postmortem astrocytes from Alzheimer disease (AD) increased GFAP reactivity and released EVs with increased Aquaporin 4 expression." (PMID 33679370, 2021). "Astrogliosis due to neuroinflammation is coupled with hypertrophy of astroglial cells and overexpression of GFAP, thus, high expression of GFAP (both GFAPα and GFAPδ) and presenilin (PS) (catalytic subunit of γ-secretase) was observed in astrocytes surrounding amyloid plagues in Alzheimer’s disease." (PMID 34202359, 2021). "Since NfL is a product of brain injury (i.e., NfL disintegrates from the axon upon damage) and GFAP is a responder to both brain injury as well as amyloid and tau aggregates, we hypothesize that GFAP serves as a more sensitive marker for Alzheimer’s disease pathological processes." (PMID 32988409, 2020). "Four hub genes, GFAP, NPY, SNAP25, and SST, were found as possibly hub aging-related genes in Alzheimer’s disease from machine algorithms by adopting the random forest, LASSO, SVM, and Boruta models." (PMID 41009659, 2025). "What is the clinical value of blood-based biomarkers (plasma phosphorylated tau217 [p-tau217], glial fibrillary acidic protein [GFAP], and neurofilament light chain [NfL]) to detect Alzheimer disease (AD) in clinical syndromes related to frontotemporal lobar degeneration (FTLD)?" (PMID 39928343, 2025). "In conclusion, plasma levels of glial fibrillary acidic protein and vesicle-associated membrane protein 2 may reflect synapse pathology independent of age and beyond general neuronal loss, even in absence of detectable Alzheimer’s disease pathology." (PMID 40620474, 2025). "Distinct immune markers were found to differentiate FTD from Alzheimer’s disease (AD) and amyotrophic lateral sclerosis (ALS), with GFAP, SPARC, and SPP1 varying between FTD and AD and IL-15, HERV-K, NOD2, and CHIT1 differing between FTD and ALS." (PMID 40305176, 2025). "FindingsWe propose a Cortical Asymmetry Index that differentiates Alzheimer’s disease (AD) from Frontotemporal dementia (FTD), distinguishes FTD subtypes, correlates with NFL and GFAP levels, and monitors FTD progression." (PMID 39934339, 2025). "To investigate the role of NOX4 in Alzheimer’s disease, we conducted immunofluorescence staining to measure the levels of NOX4 protein in GFAP-positive astrocytes in the cortical region of APP/PS1 transgenic mice and wild-type (WT) mice." (PMID 38956702, 2024). "Post hoc analyses revealed an interaction between plasma GFAP and WMH in promoting Alzheimer’s disease pathophysiology and downstream neurodegeneration, suggesting synergy between vascular and inflammatory processes in this proposed pathophysiological cascade." (PMID 39403075, 2024).
Alzheimer disease (continued). "For example, GFAP is elevated earlier in the Alzheimer’s disease process than NfL7 and in TBI, GFAP peaks within hours-to-days after ictus, much earlier than NfL, which reaches maximal levels around three weeks post-injury." (PMID 38903933, 2024). "Consequently, we might suggest different roles for GFAP and NfL, with GFAP being more informative in the earlies stages of the disease and NfL being more useful in monitoring the progression of Alzheimer's pathological changes to Alzheimer's disease." (PMID 37723371, 2024). "Neurofila-ments and glial fibrillary acidic protein (GFAP) have emerged as promising candidates for examining disease pathophysiology in neurological conditions, such as multiple sclerosis (MS), Alzheimer disease, Parkinson’s disease, and others." (PMID 39063050, 2024). "We have previously reported similar findings in an Alzheimer’s disease mouse model, where 11C-DED and GFAP follow divergent trajectories with a later detection of GFAP expression relatively to the detection of high 11C-DED binding." (PMID 37697307, 2023). "Since E. cava has shown a protective effect against NI and apoptosis, and given that NI and ND are interrelated processes, we measured glial fibrillary acidic protein (GFAP), a biomarker used to diagnose Alzheimer’s disease." (PMID 37111229, 2023). "For example, glial fibrillary acidic protein (GFAP) has more carbonylation sites in multiple sclerosis, Pick’s disease, and aging patients, but few in Alzheimer’s disease patients." (PMID 37957582, 2023). "In the brain, Alzheimer’s disease and memory-related genes (Camk2n1, Apod, and Serpina3n), and immune-response-related genes (Spp1, CD68, GFAP, Mpeg, Ddx3y, Lyz2, CTSZ, Tyrobp, C4b, and C1qa), were selected for mRNA qPCR analysis in adenine-induced CKD mice." (PMID 35447931, 2022). "Glial fibrillary acidic protein (GFAP) is a marker of reactive astrogliosis that increases in the cerebrospinal fluid (CSF) and blood of individuals with Alzheimer disease (AD)." (PMID 34661615, 2021). "They successfully tested several markers (DCX, NeuN, PSA-NCAM, GFAP, PH3, Prox1, calretinin, βIII-tubulin, and calbindin) in healthy brains, and under pathological conditions in brains from patients with Alzheimer’s disease." (PMID 34768919, 2021). "We hypothesize that boosting of glymphatic function in combination with the reduction in GFAP expression might potentially contribute to the lowered risk for Alzheimer’s disease and non-Alzheimer’s dementia among individuals with habitually low but non-zero alcohol intake." (PMID 29396480, 2018). "In models of Alzheimer’s disease and TBI, increased mIns corresponded with increased GFAP staining within the same ROI and following the same time course." (PMID 26578948, 2015). "AD, Alzheimer’s Disease; Aβ, amyloid beta; APP, amyloid precursor protein; GFAP, glial fibrillary acidic protein; Iba1, ionized calcium binding adaptor molecule 1; PSD95, postsynaptic density protein 95; TNFα, tumor necrosis factor α." (PMID 22673542, 2012). "Plasma biomarkers provide an accessible way to assess evolving brain changes; non-specific neurodegeneration (NfL, GFAP) or evolving Alzheimer’s disease (Aβ 42/40 ratio, P-Tau181)." (PMID 39820537, 2025). "Importantly, these associations were observed in absence of Alzheimer’s disease pathology and beyond GM loss, suggesting that plasma levels of VAMP2 and GFAP may reflect early synaptic alterations, not specific to Alzheimer’s disease and prior to substantial neurodegeneration." (PMID 40620474, 2025). "Plasma biomarkers can measure by-products of non-specific neurodegeneration (NfL or GFAP) or specific neuropathologies like Alzheimer’s disease (Aβ 42/40 ratio, P-Tau181)." (PMID 39820537, 2025). "Two additional Alzheimer’s disease cases without anti-GFAP autoantibodies in CSF (used as a “control”) showed complement C4d deposition only in neuritic plaques but not on astrocytes." (PMID 38310187, 2024).
Alzheimer disease (continued). "Similarly, cognitive performance in Alzheimer's disease and amyloid PET status can be predicted and classified by a combination of GFAP, amyloid beta, and neurofilament light chain." (PMID 38234075, 2024). "For example, the up-regulated levels of neurofilament light chain (NFL) and glial fibrillary acidic protein (GFAP) in serum may indicate neuronal damage in the progression of neurodegenerative diseases, such as Alzheimer’s disease or Parkinson’s disease." (PMID 36744129, 2023). "Intriguingly, the iPSC-NSCs from Alzheimer’s disease and the non-AD control cell line yielded positive immunostaining for βIII-tubulin and GFAP when cultured on Matrigel and PL Matrix." (PMID 37367039, 2023). "Moreover, PADI2 specifically citrullinates glial fibrillary acidic protein (GFAP), an astrocyte-specific marker protein found in Alzheimer’s disease (AD) patients." (PMID 32079300, 2020). "Moreover, an experimental anti-inflammatory treatment in a mouse model of Alzheimer’s disease attenuated both the increase in 1H-MRS-detectable mIns and the increase in GFAP-positive astrocytes." (PMID 26578948, 2015). "Significantly, GFAP-VIVIT expression led to improved cognitive and synaptic functions, reduced glial activation and lower amyloid levels, thereby confirming the important role of astrocytes in Alzheimer’s disease." (PMID 24098426, 2013). "In contrast to NfL, GFAP does not reflect neuroaxonal injury, but astrocyte activation evoked by CNS‐pathologies with primary or secondary inflammatory responses such as multiple sclerosis, traumatic brain injury, ischemic stroke, and Alzheimer's disease." (PMID 39831665, 2025). "In the present study, we evaluated how plasma p‐tau181, GFAP, and a marker of neurodegeneration (neurofilament light chain; NfL) differed by clinical diagnosis and related to Aβ‐PET in Hispanic and non‐Hispanic older adults from the 1Florida Alzheimer's Disease Research Center (1FLADRC)." (PMID 37671801, 2024). "The strong negative association between plasma GFAP and 11C-DED binding in Autosomal Dominant and sporadic Alzheimer’s disease brains may indicate that if both are markers of reactive astrogliosis, they may detect different states or subtypes of astrogliosis." (PMID 37697307, 2023). "When assessing 11C-DED binding in all individual cortical ROIs, significant negative correlations with plasma GFAP concentration were detected in widespread, mainly frontotemporal cortical ROIs, in both ADAD mutation carriers and patients with sporadic Alzheimer’s disease separately." (PMID 37697307, 2023). "In addition, other Alzheimer’s disease relevant biomarkers including tau isoforms, neurofilament light and glial fibrillary acidic protein were not available for both cohorts at the time of the analysis." (PMID 37942088, 2023). "Unlike other diseases (e.g., brain injury, Alzheimer’s disease, Parkinson’s disease, etc.)where astrocytic activity is increased and GFAP (glial fibrillary acidic protein) proliferation (astrogliosis) is predominant, MDD patients exhibit reduced numbers and smaller size." (PMID 36297314, 2022). "If GFAP expression is downregulated, then one could expect changes in the transcriptional patterns of astroglial cells, suggesting more pro-inflammatory phenotype, as was demonstrated in mice lacking GFAP with the transgenic model of Alzheimer’s disease." (PMID 34202359, 2021). "It has previously been shown that pelargonidin could significantly attenuate MDA and catalase activity in the hippocampus, decrease glial fibrillary acidic protein (GFAP) levels, and thereby improve memory and learning functions in a rat model of Alzheimer’s disease." (PMID 33552591, 2021). "Therefore, GFAP antibodies were titrated to label only reactive astrocytes using a well established 5xFAD model of Alzheimer's disease known to have inflammation (data not shown)." (PMID 25178488, 2014).
Alzheimer disease (continued). "The analysis of brain tissue sections obtained from uninfected individuals (uninfected, Un, and Alzheimer’s disease, Alz) showed DAPI, Alu repeats, and cellular markers (Iba-1 and GFAP), but no unspecific staining for HIV DNA, HIV-mRNA, or HIV-p24 as expected." (PMID 35954221, 2022). "Despite the associations with disease severity and cognition, it is still not clear whether both serum NfL and serum GFAP are specific for CSVD in our cohort of elderly patients or whether both biomarkers may also reflect comorbid neurodegenerative pathologies such as impending Alzheimer’ disease." (PMID 36009416, 2022).